FKBP5 (FKBP prolyl isomerase 5)
Diseases named in the same sentence as FKBP5 in open-access papers (continued):
Sharing a sentence is not in itself a finding about the gene and the disease.
depression (continued). "At present there are multiple clear examples of such G x E influences on child outcomes; for example, child maltreatment history interaction with 5-HTTLPR, CRHR1, FKBP5, and ADRB2 showing greater vulnerability to depression or PTSD as adults." (PMID 27494520, 2016). "Mediation analyses across cohorts find only modest or nonsignificant mediation of the childhood-trauma → depression link by FKBP5 methylation." (PMID 41373485, 2025). "A recent study examining sex differences in pleiotropic effects for depression and smoking found pleiotropic effects of FKBP5 on depression and smoking initiation among all participants and pleiotropy for NR3C2 and CHRNA5 for depression and cigarettes per day among females." (PMID 38790194, 2024). "There were no other group differences in NR3C1 CpGs and FKBP5 methylation in relation to the outcomes (resilience, depressive symptoms, and personality vulnerability to depression)." (PMID 39257475, 2024). "DNA methylation of NR3C1 and FKBP5 was not significantly correlated with personality vulnerability to depression, resilience levels, or with perinatal depressive symptoms." (PMID 39257475, 2024). "Stress during early development could change the FKBP5 methylation, leading to a disrupted feedback loop and slower regulation of the HPA stress reactions, which could promote the development of depressive disorders." (PMID 38338761, 2024). "For example, in one study, the frontal cortex of individuals with major depression shows increased FKBP5 expression while no change is observed with childhood maltreatment." (PMID 36781843, 2023). "Nonetheless, our results somewhat echo with the other two studies that targeted other candidate genes, such as FKBP5 and OXTR, for which DNAm levels did not explain the maltreatment-depression association." (PMID 36634080, 2023). "A correlation between depression severity and FK506-binding protein 5 (FKBP5) gene expression (a negative regulator of the glucocorticoid receptor gene) in individuals homozygous for GG of the FKBP5 single nucleotide polymorphism (SNP) rs3800373 was emphasized." (PMID 38138916, 2023). "Moreover, there was a pronounced reduction in FKBP5 gene and FKBP51 protein expression in patients with depression after 4 weeks of antidepressant treatment, but there were increases in nonresponders." (PMID 37051166, 2023). "Nevertheless, none of the examined SNPs were found to be associated with depression in colorectal cancer patients, including the deletion SNP of 5-HTTLPR, rs6295 in serotonin 1a receptor (HTR1a), rs6265 in BDNF, rs1360780 in FKBP5 and rs4680 in COMT." (PMID 35528795, 2022). "Due to the multifaceted pathogenesis of depression, this study aimed to clarify whether the KBD formula ameliorated the effect of UCMS-induced changes in expression levels of the depression-related genes BDNF, CREB, GR, SGK1, FKBP5, IL-1β, IL-6, and TNF-α." (PMID 34358084, 2021). "FKBP5−/− mice have previously demonstrated protection from depression-like behavior at 17–20 months of age, but not at 10–16 weeks." (PMID 25191701, 2014). "Interestingly, in previous work, deletion of Fkbp5 in mice did not change anxiety-related, stress-coping, or depression-like behavior under basal conditions, but led to more active-coping behavior following acute stressors, including the forced swim test." (PMID 41567824, 2026). "However, no significant changes were found in GR, HSP90, and FKBP5 expression before and after 8 weeks of antidepressant therapy in patients with major depressive disorder." (PMID 38600448, 2024). "However, some studies indicate that FKBP5 DNA methylation levels do not mediate the relationship between CM and depression." (PMID 38249586, 2023). "Second, we only explored the methylation level of the FKBP5 promoter region and did not contain other regions of the gene, such as introns 2 and 7, though the function of the promoter region is also closely related to depression." (PMID 36451133, 2022).
depression (continued). "It has been demonstrated that the function of the GR is impaired during the development of depression due to the high expression level of FKBP5 that leads to destabilizing the negative response and an increasing level of glucocorticoids called “glucocorticoid resistance”." (PMID 36451133, 2022). "In conclusion we could not show an association between depression measurements as assessed by EPDS values during or after pregnancy and candidate haplotypes in the genes FKBP5, NR3C1, and CRHR1." (PMID 24741566, 2014). "Thus, this study could not fully reflect the association of the polymorphisms of FKBP5 with comorbid CAD and depression." (PMID 32547886, 2020). "The association between TESI and the SNPs rs737054 (TT genotype) in FKBP5 and rs2963155 (GG/AG genotypes) in NR3C1 did not remain significant after adjustment for depression severity changes." (PMID 32952155, 2020). "Third, the data on FKPB51 level were insufficient, and we failed to assess the influence of FKBP5 expression on the incidence of comorbid CAD and depression by regulating the FKPB51 level." (PMID 32547886, 2020). "Our data demonstrated that wild-type mice have an age-dependent increase in depression-like behavior and circulating CORT levels that was absent in FKBP5−/− mice, indicating these age-related changes were mediated by increasing FKBP51 expression with age." (PMID 25191701, 2014).
Anxiety (85 papers, 2011 to 2026). Intense feelings of nervousness, tension, or panic often arise in response to interpersonal stresses. "In the Flasbeck study, higher methylation at an intron 7 FKBP5 locus (which regulates glucocorticoid receptor sensitivity) was associated with increased anxiety symptoms and greater overall symptom severity." (PMID 41303216, 2025). "When genotyping FKBP5 in an AD cohort, a synergistic effect of its alleles and the APOE genotype on anxiety scores and a sex‐dependent effect of FKBP5 promoter methylation on neurophysiological brain activity has been observed." (PMID 39737748, 2025). "The co-chaperone FKBP51, encoded by FKBP5 gene, is recognized as a psychiatric risk factor for anxiety and depressive disorders due to its crucial role in the stress response." (PMID 39438757, 2025). "FKBP51 and its encoding gene, FKBP5, have drawn significant scientific attention due to their links to various stress‐related disorders, including anxiety, depressive disorders, post‐traumatic stress disorder (PTSD), obesity, and suicide." (PMID 39225086, 2024). "While studies on anxiety in this context are limited, some reports suggest an association between anxiety and the presence of the FKBP5 gene." (PMID 38540098, 2024). "While fewer studies focus specifically on GAD, findings suggest associations between NR3C1 and FKBP5 methylation and anxiety symptomatology." (PMID 38792892, 2024). "Flasbeck and Brüne explored the association between FKBP5 methylation and anxiety, providing insights into the gene’s involvement in emotional regulation and empathy." (PMID 38792892, 2024). "Overexpression of FKBP5 as a result of decreased FKBP5 methylation in the amygdala is associated with the anxiety phenotype in adult rats." (PMID 35998298, 2023). "Conversely in adults, reduced DNA methylation at the FKBP5 gene has been associated with a greater response to psychological therapy for agoraphobia, and reduced anxiety following treatment." (PMID 39816863, 2023). "Anxiety can cause the upregulation of FKBP5, resulting in a lowered affinity of GRs to GCs when sustained, leading to clinical symptoms of anxiety and MDD." (PMID 37398599, 2023). "The product encoded by FKBP5 affects glucocorticoid receptor sensitivity and the biological effects of stress and anxiety." (PMID 36834016, 2023). "In rodent models, heightened FKBP5/1 expression in the brain has been shown to cause psychiatric-like phenotypes, including impaired stress-coping behaviour, increased anxiety and weakened extinction learning." (PMID 36729133, 2023). "We attempted for the first time to combine in one study the analysis of the effects of rs1360780 polymorphism in the FKBP5 gene and ε2/ε3/ε4 polymorphisms in the ApoE gene on anxiety levels and EEG parameters." (PMID 35205209, 2022). "In contrast, the three examined SNPs in the FK506 binding protein 5 (FKBP5–rs1360780; rs9296158; rs9470080), a gene implicated in stress response, appeared to have a genotype by time interaction effect on anxiety levels among patients." (PMID 35528795, 2022). "Fourth, it is possible that our study was underpowered to detect the associations between FKBP5 methylation and anxiety symptoms." (PMID 35185646, 2022). "Previous studies have shown that alteration in DNA methylation of the FKBP5 gene is associated with mental disorders such as anxiety or depression." (PMID 35185646, 2022). "Our data suggest a synergistic effect of the stress-associated (FKBP5) and neurodegeneration-associated (ApoE) gene alleles on anxiety and the gender-dependent effect of FKBP5 on neurophysiological brain activity." (PMID 35205209, 2022). "Together, our findings provide evidence that prenatal trauma has a long-term impact on stress axis function and anxiety phenotype associated with altered Crhr1 and Fkbp5 transcripts and promoter methylation." (PMID 33758173, 2021). "Increased FKBP5 expression in specific brain regions is associated with increased stress responsiveness and anxiety." (PMID 33673722, 2021).
Anxiety (continued). "Decreased scores of the factor characterized by FKBP5 methylation were associated with maternal pregnancy-related anxiety only in boys." (PMID 34715840, 2021). "Decreasing DNA methylation at one CpG site of intron 7 of FKBP5 was strongly associated with decreasing anxiety severity following exposure‐based CBT." (PMID 30334356, 2019). "In this study, we demonstrate changes in DNA methylation at FKBP5 intron 7 associated with reduction in anxiety severity following exposure‐based CBT." (PMID 30334356, 2019). "For example, glucocorticoid administration to adolescent mice reduces methylation of the FKBP5 gene in the hippocampus, hypothalamus, and blood, which is associated with enhanced expression of FKBP5 and increased anxiety-like behavior." (PMID 23584113, 2012). "Interestingly, a recent publication revealed that loss of Fkbp5 in glutamatergic and GABAergic neurons of older aged mice leads to opposite effects on anxiety only in females and on fear memory only in males." (PMID 37726498, 2024). "Association of DNA methylation in FKBP5 gene with anxiety symptoms at follow-up." (PMID 35185646, 2022). "Since the T allele of rs1360780 in the FKBP5 gene was associated not only with depressive behavior but also with the development of various mental diseases, we decided to study the effect of this polymorphism on the level of anxiety." (PMID 35205209, 2022). "Finally, we analysed the association of the FKBP5 promoter methylation status with the anxiety level and EEG features in carriers of both risk alleles." (PMID 35205209, 2022). "Together, these results suggest that transient peripheral inflammation in mice can induce the Fkbp5 gene expression but not anxiety or anhedonia after recovery from the sickness; whereas Fkbp5 deficiency causes heightened anxiety response following peripheral inflammation." (PMID 35705957, 2022). "However, in the present study, Fkbp5-KO mice exhibited higher vulnerability to inflammation-associated anxiety." (PMID 35705957, 2022). "Additionally, our final multiple linear regression models showed that DNA methylation of the promoter region of the FKBP5 gene showed an association with anxiety symptoms at follow-up after adjusting for the covariates." (PMID 35185646, 2022). "The results of our study showed that the level of state anxiety on the Spielberger scale was higher in carriers of the T and ε4 alleles from a population of different ages in the FKBP5 and ApoE genes, respectively, than in carriers of the T allele who lack the ε4 allele." (PMID 35205209, 2022). "There is evidence from preclinical studies that increased FKBP5 expression in specific brain regions is associated with risk-promoting sleep architecture and with increased stress responsiveness and anxiety, all of which are associated with increased vulnerability to psychiatric disorders." (PMID 33673722, 2021). "Moreover, studies in mice have showed that long-tern exposure to Glucocorticoid reduced DNA methylation of Fkbp5 in the hippocampus and hypothalamus, and the demethylation was associated with anxiety-like behavior." (PMID 34830120, 2021). "Furthermore, only boys showed differential methylation of the FKBP5 gene in response to prenatal pregnancy-related anxiety; also, methylation of NR3C1 and HSD11B2 genes was associated with the risk of emotional symptoms and hyperactivity only in boys." (PMID 34715840, 2021). "Since our study setup and aim did not include such a test, we could not establish any relationship between the polymorphism in the FKBP5 gene and self-assessed anxiety after psychological stress." (PMID 32957930, 2020). "An increased knowledge of the molecular mechanisms underlying these interactions may help determine if FKBP5 could be an effective target for the treatment of anxiety and other mood-related illnesses." (PMID 31167373, 2019).
Anxiety (continued). "The present study examined whether FKBP5 variability moderated the association of LEs with depressive symptoms, state-anxiety, neuroticism, and social anxiety." (PMID 29466454, 2018). "FKBP5 variability has also been shown to be associated with heightened amygdala reactivity in the context of emotional neglect, increased attentional threat bias and differences in hippocampal shape, and with anxiety-proneness trait levels." (PMID 29466454, 2018). "Also, Flasbeck and Brüne demonstrated that FKBP5 was associated with anxiety and reduced empathy." (PMID 38792892, 2024). "Thus, we demonstrate for the first time the gender-specific effect of the rs1360780 polymorphism in the FKBP5 gene on the characteristics of the electrical activity of the brain and the development of anxiety, both influenced by the allelic polymorphism in the ApoE gene." (PMID 35205209, 2022). "Finally, we assessed the moderating influence of candidate genes whose level of methylation is associated with the Nr3c1 genotype on anxiety-like behavior: Ank3, Avp, Avpr1a, Avpr1b, Bdnf, Cacna1c, Cyp11b1, Cyp11b2, Fkbp5, Hsd11b1, Igf2, Morc1, Nr3c1, Oxt, Oxtr, Pclo, Slc6a4." (PMID 30655507, 2019). "Using both viral and pharmacological tools, we further showed that Fkbp5 signaling in the amygdala modulates anxiety-like behavior, supporting FKBP5 as a promising target for therapeutic intervention." (PMID 41018719, 2025). "The brain-derived neurotrophic factor (BDNF), catecholamine-O-methyltransferase (COMT), and FK506-binding protein 5 (FKBP5)-gene are other possible genetic markers for altered anxiety levels." (PMID 40094863, 2025). "After contextual fear extinction trials, we measured FKBP5 protein expression, due to its association with PTSD and anxiety-like behaviors, within the dHPC, BLA and striatum of previously injected mice." (PMID 39484582, 2024). "The detection of key proteins such as FKBP5, which when downregulated showed rescue from the anxiety phenotype, also offer attractive avenues for future pharmacological interventions." (PMID 35998298, 2023). "Similar findings, with decreased FKBP5 methylation detected in saliva samples associated with better CBT outcomes, were also reported in a cohort of children diagnosed with anxiety between the ages of 8–15 years." (PMID 35998298, 2023). "We found that Fkbp5 deletion produced a strong anxiety response after recovery from LPS-induced sickness." (PMID 35705957, 2022). "Another study reported that mice with a deficiency in Delta-like 2 (a member of the NOTCH ligand family) gene (Dlk2) exhibited downregulated Fkbp5 expression and increased vulnerability to anxiety-like behavior." (PMID 35705957, 2022). "We observed that increased state anxiety scores depend on the combination of the FKBP5 and ApoE genotypes and on the DNA methylation state of the FKBP5 promoter and ApoE genotype." (PMID 35205209, 2022). "In our transient systemic inflammation model, we found that the anxiety level of Fkbp5-KO mice was higher than that of WT mice despite both these groups exhibiting similar transient sickness behavior." (PMID 35705957, 2022). "To examine the role of FKBP51 in inflammation-induced anxiety, we treated 12-week-old WT and Fkbp5-KO mice with a single bolus intraperitoneal injection of the bacterial endotoxin LPS (3 mg/kg of body weight)." (PMID 35705957, 2022). "GC-induced anxiety was also examined, which was attenuated in Fkbp5-KO and hippocampal GAD65 expression was unaffected." (PMID 35705957, 2022). "Methylation of FKBP5 (bin 2) correlated with anxiety (SCL-90-R) and the global psychopathological symptom load index (GSI), as well as with lower empathic perspective-taking abilities." (PMID 33705478, 2021). "Our genetic manipulation of native Fkbp5 expression in the ovBNST demonstrates the central role of this cochaperone in regulating anxiety-related behavior." (PMID 34872938, 2021).